KMO (kynurenine 3-monooxygenase)
Description:
Catalyzes the hydroxylation of L-kynurenine (L-Kyn) to form 3-hydroxy-L-kynurenine (L-3OHKyn). Required for synthesis of quinolinic acid, a neurotoxic NMDA receptor antagonist and potential endogenous inhibitor of NMDA receptor signaling in axonal targeting, synaptogenesis and apoptosis during brain development. Quinolinic acid may also affect NMDA receptor signaling in pancreatic beta cells, osteoblasts, myocardial cells, and the gastrointestinal tract (Probable).
Synonyms: dJ317G22.1
Tractability: Small molecule: a structure with a bound ligand is known; a high-quality ligand is known; it belongs to a druggable protein family. Antibody: UniProt predicts a signal peptide or a membrane-spanning region. PROTAC: its protein half-life has been measured; a small molecule that binds it is known.
Target class: Enzyme; Oxidoreductase
Gene: Protein-coding gene on chromosome 1 (241,532,134 to 241,595,642, forward strand). Ensembl gene ENSG00000117009.
Subcellular location: Mitochondrion outer membrane
Pathways (Reactome):
Metabolism: Tryptophan catabolism
Gene Ontology:
Molecular function: FAD binding; kynurenine 3-monooxygenase activity; NAD(P)H oxidase H2O2-forming activity; flavin adenine dinucleotide binding
Biological process: L-tryptophan catabolic process; NAD+ metabolic process; 'de novo' NAD+ biosynthetic process from L-tryptophan; cellular response to interleukin-1; cellular response to lipopolysaccharide; kynurenic acid biosynthetic process; NAD+ biosynthetic process; positive regulation of glutamate secretion; positive regulation of glutamate secretion, neurotransmission; quinolinate biosynthetic process; response to lipopolysaccharide
Cellular component: mitochondrial outer membrane; mitochondrion; extracellular region; mitochondrial membrane
Genetic constraint (gnomAD): Loss-of-function variants: 10 observed, 22.48 expected, observed/expected ratio (o/e) 0.44, 90% interval 0.27 to 0.75. The upper end of that interval is the gene's LOEUF score, 0.75, which puts it in group 3 of 6, group 1 being the genes least tolerant of losing a copy. Missense variants: 269 observed, 346.66 expected, observed/expected ratio (o/e) 0.78, 90% interval 0.7 to 0.86. Synonymous variants: 127 observed, 118.25 expected, observed/expected ratio (o/e) 1.07, 90% interval 0.93 to 1.25.
Gene-disease validity (ClinGen):
ClinGen rates the evidence that KMO causes each of these diseases.
pellagra (autosomal recessive): No Known Disease Relationship.
Homologues: Orthologues: chimpanzee KMO (96% identical), macaque KMO (90% identical), rabbit KMO (85% identical), dog KMO (83% identical), guinea pig KMO (81% identical), pig KMO (78% identical), mouse Kmo (78% identical), rat Kmo (77% identical), zebrafish kmo (60% identical), tropical clawed frog kmo (58% identical), Caenorhabditis elegans kmo-1 (42% identical), Caenorhabditis elegans kmo-2 (31% identical). Paralogues in human: COQ6 (17% identical).
Diseases named in the same sentence as KMO in open-access papers:
KMO is named in the same sentence as 107 diseases in open-access papers, as found by Europe PMC text mining. Sharing a sentence is not in itself a finding about the gene and the disease. The quoted sentences say what the papers report.
schizophrenia (27 papers, 2014 to 2026). A major psychotic disorder characterized by abnormalities in the perception or expression of reality. "KMO activity has been implicated in several major brain diseases including Huntington’s disease (HD) and schizophrenia." (PMID 35204197, 2022). "Alterations in KA are associated with schizophrenia physiopathology, elevated levels of KA are found in CSF and cortical areas along with reduced KMO activity that suggests imbalance between the two main branches of KP." (PMID 34205235, 2021). "Multiple clinical studies have reported the association of two SNPs in schizophrenia patients, rs1053230 and rs2275163, located on the KMO gene." (PMID 34205235, 2021). "KMO gene polymorphisms influence CSF KYNA levels in patients with schizophrenia and bipolar disorder." (PMID 32414200, 2020). "Altogether, the inhibition of KMO treatment of schizophrenia is clear and effective, but its peculiar susceptibility is the focus of research." (PMID 32148781, 2020). "KMO polymorphism (rs1053230) shows a correlation with increased CSF kynurenine acid levels in schizophrenia patients." (PMID 32341334, 2020). "In contrast, KMO activity is reduced in the prefrontal cortex in schizophrenia, with associated shifts in the kynurenine pathway toward the production of KYNA." (PMID 28446679, 2017). "Present results (together with our previously published data) suggest that peripheral KMO deficiency is a common feature of MetS and schizophrenia." (PMID 28748226, 2017). "KMO is a pivotal enzyme of the kynurenine pathway of tryptophan metabolism and has been associated with schizophrenia and induction of depression." (PMID 27832807, 2016). "The impact of KMO polymorphism in the KP has been investigated only in schizophrenia and bipolar disease." (PMID 25785227, 2015). "Human studies point to a causal relationship between intronic Kmo SNP, rs2275163, and neurocognitive deficits frequently reported in patients with schizophrenia and psychotic bipolar disorder, and postmortem brain tissue analysis suggest an association between Kmo SNPs and reduced KMO activity." (PMID 40176166, 2025). "Notably, of the three enzymes that use Kyn as a substrate, KAT and kynureninase are unsaturated enzymes that are able to utilize the increased availability of Kyn resulting from KMO deficiency (e.g., in the brains of individuals with schizophrenia)." (PMID 39769034, 2024). "Considering that accumulated metabolites produced by KMO dysregulation are involved in neurotoxicity, increased KMO may be another factor associated with schizophrenia-relevant behaviors in amphetamine-sensitized mice." (PMID 32341334, 2020). "Moreover, an intronic SNP within the human KMO gene is associated with reduced KMO mRNA expression and impaired schizophrenia-related endophenotypes." (PMID 24567701, 2014). "Additionally, KMO intronic SNP rs2275163 is associated with schizophrenia endophenotypes." (PMID 42239117, 2026). "Animal studies have shown that the impairment of KMO, as observed in the brains of individuals with schizophrenia, results in the upregulation of both KYNA and AA formation." (PMID 39769034, 2024). "KMO impairment in schizophrenia-specific brain areas (e.g., Brodmann area 10) increases the availability of Kyn as a substrate for both kynureninase and KAT." (PMID 39769034, 2024). "Contributing to enhanced production of KynA, the expression and enzyme activity of kynurenine 3-monooxygenase (KMO) are reduced in schizophrenia." (PMID 34393855, 2021). "Haplotype analysis shows an association between kynurenine 3-monoxygenase (KMO) gene polymorphisms and CSF concentrations of KYNA in patients with schizophrenia." (PMID 32414200, 2020). "High levels of KYNA in the prefrontal cortex of patients with schizophrenia can be due to reduced activity of kynurenine 3-monooxygenase (KMO), because reduction in KMO expression and its enzyme activity have been reported in the patient’s brain." (PMID 32796766, 2020).
schizophrenia (continued). "It is known that KMO inhibitors rise KYNA levels, and the KMO gene is positioned in the chromosomal region related to schizophrenia, 1q42‐q44." (PMID 32148781, 2020). "Patients with schizophrenia display a significant reduction in KMO gene expression, and an increase in brain and cerebrospinal fluid (CSF) concentrations of the endogenous N‐methyl‐d‐aspartate receptor antagonist." (PMID 32148781, 2020). "Specifically, we expected to find mRNA levels of TDO and KATI/II mRNAs to be increased in schizophrenia and KMO mRNA to be decreased in schizophrenia, particularly among those patients in the high cytokine subgroup." (PMID 30940904, 2020). "This increased activity of astrocytes in schizophrenia and the persistent reduction of microglial KMO activity result in increased kynurenic acid formation in astrocytes." (PMID 32061259, 2020). "Recently, parecoxib given intravenously was reported to lower the firing activity of dopaminergic neurons in kynurenine 3-monooxygenase knock-out mice, a novel animal model of schizophrenia." (PMID 30178287, 2019). "The expression KMO is reduced in schizophrenia and in bipolar patients with a history of psychosis, and two KMO SNPs were found frequently in schizophrenia patients compared with healthy controls." (PMID 29616208, 2018). "It is possible that enzymes of the kynurenine pathway other than KMO are altered in schizophrenia and that antipsychotic drugs regulate the pathway at multiple levels." (PMID 26643205, 2015). "Schizophrenia impairs the ability of kynurenine 3-monooxygenase (KMO) to function by inhibiting it." (PMID 40566484, 2025). "The inhibition of KAT by estrogens might contribute to female-specific AA elevation, considering that Kyn is a common substrate for both kynureninase and KAT, while KMO activity is downregulated in individuals with schizophrenia." (PMID 39769034, 2024). "Elevated levels of kynurenate have been observed in the postmortem brain tissue of individuals with schizophrenia, while rats treated with kynurenine-3-monooxygenase inhibitors have reduced prepulse inhibition, indicating the dopaminergic hyperactivity associated with schizophrenia." (PMID 38673018, 2024). "Considering that KMO is already impaired in individuals with schizophrenia, one may suggest that the inhibition of KAT would increase Kyn availability as a substrate for kynureninase, consequently leading to a robust increase in AA formation." (PMID 39769034, 2024). "At this point, some researchers also found that major susceptibility to schizophrenia is not conferred by KMO single nucleotide polymorphisms (SNPs) per se." (PMID 32148781, 2020). "In the bipolar disorder and schizophrenia patients, KMO mRNA levels are reduced in the brain compared with nonpsychotic patients and controls, and the KMO Arg452 allele is associated with increased levels of CSF KYNA and reduced brain KMO expression." (PMID 32414200, 2020). "Also, increased intracerebral KYNA in schizophrenia is related to decreased KMO enzyme activity in microglia." (PMID 30940904, 2020). "This suggests that KMO is a reliable candidate gene for schizophrenia." (PMID 32148781, 2020). "We are not aware of previous studies of KMO single nucleotide polymorphisms (SNPs) in PD, though some KMO SNPs have been investigated in schizophrenia and bipolar disease." (PMID 25785227, 2015). "The kynurenine pathway generates a number of neuroactive metabolites that might be directly implicated in the pathophysiology of schizophrenia, of which QUINA and XA lie downstream of KMO, whereas KYNA is a direct metabolic product of KYN." (PMID 26643205, 2015). "Whereas the rs1053230 variant of the KMO may not influence cognitive aspects but is strongly associated with higher risk of developing schizophrenia associated behaviors." (PMID 34205235, 2021). "However, support for KMO polymorphism does not confer primary susceptibility to schizophrenia itself." (PMID 32148781, 2020).
schizophrenia (continued). "Thus, disease-relevant genetic impairment of KMO expression/activity might play a contributing role in the overproduction of KYNA in schizophrenia and related psychiatric disorders." (PMID 24567701, 2014). "For example, in a rat model of schizophrenia, inhibitors of TDO, IDO and KMO were able to prevent lipid peroxidation, decrease protein carbonyl levels, and increase SOD levels and catalase activity." (PMID 35682980, 2022). "In contrast, we detected moderately strong, significant inverse correlations of KMO mRNA levels to IL-1β and SERPINA3 mRNA levels within the PFC of people with schizophrenia." (PMID 30940904, 2020). "Serum levels of kynurenine metabolites that lie downstream of KMO (i.e., 3-HK, XA, 3-HANA, and QUINA) were largely reduced in patients affected by schizophrenia, whereas levels of KYNA and ANA, which originate from KYN via KMO-independent reactions, were increased." (PMID 26643205, 2015). "KAT I/II mRNA is mainly produced in astrocytes and we find that KATI/II mRNA was increased in the brains of people with schizophrenia who were in the high cytokine subgroup, whereas KMO mRNA was not statistically different according to diagnosis or cytokine status." (PMID 30940904, 2020). "The search for understanding this mechanism also in humans, mostly in patients with schizophrenia, will allow to conduct future studies that could regulate the KMO-genetic expression and finally to avoid the imbalance between KNYA and QUIN mechanisms, as showed in patients with schizophrenia." (PMID 32061259, 2020).
depression (25 papers, 2010 to 2025). "The key innovation of this study is the clear and systematic demonstration that inhibiting KMO activity significantly ameliorates the core behavioral symptoms of epilepsy-associated depression (e.g., anhedonia and behavioral despair) and cognitive dysfunction." (PMID 41020827, 2025). "Although this study has made significant progress in revealing the potential therapeutic effects of KMO inhibitors on epilepsy-associated depression, it has some limitations." (PMID 41020827, 2025). "The dopaminergic metabolism in bipolar disorder, depression, and schizophrenia, has been reported to be impaired by KMO gene polymorphism." (PMID 34201647, 2021). "Laumet and co-workers demonstrated the involvement of IL-1β in nerve injury-induced depression associated with enhanced KMO mRNA brain expression and activity in mice brain." (PMID 34072767, 2021). "Some polymorphisms of the IDO1, 2 and KMO encoded genes are identified in patients with depression." (PMID 34072767, 2021). "Using this approach, we investigated the effects of KMO inhibition on seizures, depressive-like behaviors, and cognitive function in epileptic mice, thereby providing novel insights and a robust scientific foundation for developing therapeutic strategies targeting epilepsy-associated depression." (PMID 41020827, 2025). "The present study establishes the centrality of KMO-mediated toxic branching off of the kynurenine metabolic pathway in epileptic co-morbid depression." (PMID 41020827, 2025). "Ablation of IDO and KMO functions effectively mitigates depression-like behaviors following chronic pain, providing novel therapeutic targets for attenuating depression comorbidity." (PMID 38851750, 2024). "Ample evidence suggests there is increased inflammation in patients with depression, and the reduced KYNA/3-HK ratio in patients with depression further confirms this, suggesting that the KMO pathway is activated as a result of depression." (PMID 36295852, 2022). "Further model analysis demonstrated that the inhibition of both serotonin transport and kynurenine-3-monooxygenase decreased the levels of DOPAL and 5-HIAL and the neurotoxic risk often associated with depression." (PMID 33970902, 2021). "The KMO knockout prevents accumulation of lipopolysaccharide-induced KP neurotoxic metabolites in the dorsal hippocampus and emergence of depression-like behaviors." (PMID 33994977, 2021). "The field of metabolic enzymes of KP, in addition to IDO/TDO, decreased activity of KAT, KMO activation, and single nucleotide polymorphisms of KMO and KATIII, are also associated with depression; however, the scale of the study is still limited." (PMID 34127024, 2021). "Inflammatory stimuli can undoubtedly alter kynurenine metabolism favoring neurotoxic metabolism through KMO, which appears to contribute to the mechanism by which inflammation results in depression and related behaviors." (PMID 26347662, 2015). "It is also possible that downstream metabolism of TRP through the KMO pathway is an important contributor to prolonged depression." (PMID 21167054, 2010). "In addition to IDO and TDO, other KYN metabolic enzymes are associated with depression, including KAT activity, KMO activation, KMO, and KAT III single-nucleotide polymorphism." (PMID 39408347, 2024). "KMO inhibition was also envisioned to counter the detrimental effects of repeated stress or excessive immune activation, which have been proposed to play key roles in depressive disorders by increasing 3-HK and quinolinic acid levels in the brain." (PMID 35204197, 2022). "KMO has been found essential for inflammation-induced depression in rodents, suggesting the present results could be of high clinical relevance." (PMID 34180293, 2021).
depression (continued). "Induction of IDO, KMO, and KYNU by proinflammatory cytokines which cause disruption of normal physiological metabolism of tryptophan and/or kynurenine appears to be an important link in the cascade of events leading to certain forms of depression." (PMID 24567701, 2014). "Etiological classification of depression expressed by peripheral (TPH1, TDO, IDO) and central (TPH2, KMO) enzymes of tryptophan metabolism may enable depression to be viewed as a clear box, with the inner components available for inspection and treatment." (PMID 25540092, 2014). "The described etiological classification expressed by peripheral (TPH1, TDO, IDO) and central (TPH2, KMO) enzymes allows depression to be viewed as a clear box with the inner components, or logic, available for appropriate individualized inspection and treatment." (PMID 25540092, 2014). "It is possible that KMO activation is related to depression." (PMID 25540092, 2014). "Moreover, there is evidence that inhibition of IDO1, TDO, and KMO or other interventions targeting Trp metabolism (like diet or probiotics) may further improve neurobehavioral manifestations including CRF or depression." (PMID 32153576, 2020). "The IDO-1, IDO-2, and KMO enzymes, along with the KYN metabolites, have also been reported to contribute to neuropathic pain, as well as migraine, headache, depression etc.." (PMID 34201647, 2021). "Potentially, all types of depression can be expressed through combinations of these key enzymes using a matrix with peripheral (TPH1, TDO, IDO) and central (TPH2, KMO) determinants." (PMID 25540092, 2014). "KMO inhibition has been shown to ameliorate the outcome of several neurological disorders, and increased levels of QUIN are reported in suicidal patients and patients with severe depression." (PMID 28446679, 2017). "IDO1, TDO, KMO, and KAT inhibitors are also under investigation, mainly for cancer and not depression purposes." (PMID 35955633, 2022).